UHRF1 (ubiquitin like with PHD and ring finger domains 1)
Diseases named in the same sentence as UHRF1 in open-access papers (continued):
Sharing a sentence is not in itself a finding about the gene and the disease.
tumor (continued). "Interestingly, UHRF1 downregulation in RCC cell lines induced the upregulation of TXNIP expression and apoptosis, suggesting that UHRF1 inhibits the expression of TXNIP in RCC through epigenetic mechanisms, thereby promoting tumor progression." (PMID 33922029, 2021). "Furthermore, expression levels of UHRF1, EZH2, TTF2, WHSC1 and RAD54L transcripts correlated significantly with the tumor stages of NSCLC patients (P<0.05)." (PMID 33658396, 2021). "This property of UHRF1 targeting may be conducive to development of efficient combination therapies as it would improve the efficacy and selectivity of conventional chemotherapy regimens composed of nontargeted drugs against tumor cells without a risk of complications involved in DNA methylation." (PMID 32840881, 2021). "We also compared the expression levels of UHRF1 protein in MM primary tumor cells and MM cell lines with normal hPBMCs." (PMID 32213189, 2020). "To test this hypothesis, we treated UHRF1-depleted CRC cells with trichostatin A (TSA), a HDAC inhibitor, and assessed the expression of well-characterized tumor suppressor genes silenced by CpG island hypermethylation." (PMID 31064417, 2019). "For most sections with high tumor cell density, both UHRF1 and XRCC4 are highly expressed in an indistinguishable manner." (PMID 29415984, 2018). "Furthermore, we confirmed our data in xenograft tumor tissue, and the results showed that IL-8, TGF-α and TNF-α were attenuated in UHRF1 suppressed group." (PMID 30174788, 2018). "These tumor-promoting functions of UHRF1 are known to be mediated by both epigenetic and non-epigenetic mechanisms." (PMID 29415984, 2018). "In parallel with these observations, the negative modulation of UHRF1 in cells possessing abundant UHRF1 increased the migratory and invasive properties of these cells, as well as tumor growth and lung metastasis." (PMID 28584306, 2017). "As UHRF1 downregulation increased both migration and invasion in vitro and is involved in hypoxia-induced EMT, we investigated whether it contributes to tumor growth in vivo." (PMID 28584306, 2017). "Additionally, we determined that both UHRF1 mRNA and protein were expressed at significantly higher levels in HCC patients with advanced TNM tumor stage, tumor microemboli, metastasis, and tumor relapse." (PMID 28060737, 2017). "Enhanced expression of UHRF1 was also observed at both mRNA and protein level in GBC-SD and NOZ cell lines and depletion of UHRF1 by siRNA or shRNA markedly reduced their migration potential in vitro and tumor forming capabilities." (PMID 28881702, 2017). "However, despite the crucial character of the integrity of the DNMT1/PCNA/UHRF1 complex, the integrity of other DNMT1 including complexes plays a major role in the inheritance of DNA methylation and in tumor development and progression." (PMID 24637615, 2014). "Furthermore, UHRF1 and EZH2 have been proposed to synergistically promote inactivation of oncosuppressor genes, among which Nkx3.1 and Msmb, in tumor cells." (PMID 23675307, 2013). "Expression levels of UHRF1 in tumours of grade-II and grade-III were upregulated compared with normal bladders by Mann–Whitney's U-test (P=0.0033 and 0.0041, respectively)." (PMID 19491893, 2009).
tumor (continued). "By investigating the transcriptional changes in HB tumor cells on CM-272 exposure, we have detected transcriptional downregulation of the survival factor IGF2 and subsequently reduced activity of PI3K-AKT signaling as the main target of the dual inhibition of UHRF1-driven consequences." (PMID 38285887, 2024). "Ectopic overexpression of UHRF1 did not affect tumor cell proliferation or migration, which may have resulted from functional redundancy." (PMID 37380646, 2023). "Although the exact consequences of PtdIns5P interaction with UHRF1 in vivo are not clear, UHRF1 is often upregulated in tumour cells, and targeting the allosteric PtdIns5P interaction site may have therapeutic value." (PMID 37509085, 2023). "However, our data show that subcutaneous injection of MCF10A cells exposed to FolateRDI/Diuron3MAC/PFOA3MAC does not induce tumor formation as does the injection of MCF10A cells that have lost the integrity of the DNMT1/PCNA/UHRF1 complex." (PMID 36278678, 2022). "Furthermore, overexpression of miR-520d, but not its mutant, abrogated PGE2-induced tumor UHRF1 upregulation." (PMID 35664070, 2022). "Moreover, the Uhrf1-TTD-KI mice had a significantly reduced number of large-size tumors (tumors with diameter L ≥ 3 mm and 3 > L ≥ 2 mm) than wild-type mice, although the difference in tumor lesions with a size smaller than 2 mm is less significant." (PMID 33947834, 2021). "Furthermore, the level of DNA methylation in tumors from Uhrf1-TTD-KI mice was substantially lower than that in tumors from the wild-type mice, indicating that reduced DNA methylation in Uhrf1-TTD-KI mice was inherited to tumor cells." (PMID 33947834, 2021). "Hence, further studies should explore detailed mechanisms of tumor suppression ability, especially the interaction between UHRF1BP1 and UHRF1, which may play important roles in tumor DNA methylation transferring and other epigenetic events." (PMID 32117775, 2020). "However, in some tumoral cell lineages, UHRF1 and UHRF2 exerted negative transcriptional influence on the expression of p2150." (PMID 31024001, 2019). "However, the regulatory relationship between RP11-424C20.2 and UHRF1 in tumor progression has not been elucidated." (PMID 31442209, 2019). "However, not all patients suffering from tumor metastasis or recurrence had elevated UHRF1 expression, and Cox proportional hazard analysis did not indicate UHRF1 expression as an independent prognostic marker for HCC." (PMID 28060737, 2017). "Conversely, this study supports a model that enhanced DNA repair capacity driven by UHRF1‐mediated XRCC4 upregulation may protect RB cells against endogenous DNA damage‐induced cell death and thereby may promote outgrowth of malignant RB cells during tumor progression." (PMID 32840881, 2021). "Thus, despite the general requirement for UHRF1 to maintain DNA methylation without bias toward specific genes, the involvement of UHRF1 in the epigenetic silencing of large numbers of tumor-related genes remains unclear." (PMID 31064417, 2019). "However, tumor tissues with relatively intact retinal structure showed denser XRCC4 staining in the regions where UHRF1 is highly expressed, implying that UHRF1 expressed during tumorigenesis of retina may further promote the XRCC4 expression." (PMID 29415984, 2018). "An analysis of the correlation between UHRF1 expression and that of its target genes in scT‐LBLs demonstrated that the tumour suppressor genes FOXP1, PIK3R1 and KLF6 exhibited a significant negative correlation with UHRF1 expression." (PMID 40579780, 2025). "However, combined experimental evidence in cell lines and mouse models along with the unusual DNMT biology observed in RB cells suggest that tumor‐promoting functions of UHRF1 in RB are largely independent of its role in DNA methylation and may involve other epigenetic mechanisms." (PMID 32840881, 2021).
tumor (continued). "We found that overexpression of UHRF1 was significantly correlated with the Gleason score, pathological stage, preoperative PSA level, and BCR, but not with age, LN status, tumour margins, or capsular invasion." (PMID 26884069, 2016).
infection (10 papers, 2016 to 2024). The state of being infected such as from the introduction of a foreign agent such as serum, vaccine, antigenic substance or organism. "UHRF1 deletion decreased active infection in primary activated CD4+ T cells and increased latency reversal in JLat and primary resting CD4+ T cell models." (PMID 38411080, 2024). "Both roles can be considered pro-viral, as UHRF1 is needed for effective initial infection, and its maintenance of latency aids long-term infection in the host." (PMID 38411080, 2024). "The other exception was UHRF1, which was strongly downregulated in aggregates but unaffected by the other infection types." (PMID 34925266, 2021). "Cytochalasin D-treated T. gondii were still able to stimulate UHRF1 promoter activity at 3 h of infection." (PMID 31492965, 2020). "We have previously shown that, contrary to its promoter activity, UHRF1 protein levels continuously increase up to 24 h post-infection." (PMID 31492965, 2020). "A twofold increase of phosphorylated UHRF1 was detected upon infection with RH WT, whereas this increase was less obvious with RHΔROP16 parasites." (PMID 31492965, 2020). "A significant increase in cyclin B1 levels was observed at 12 h of infection in UHRF1 knock-down cells, compared with cells transfected with EGFP-siRNA, whereas lower expression is seen for earlier time points." (PMID 31492965, 2020). "We also found that infection-induced upregulation of UHRF1 expression is responsible for the host cell arrest at the G2 phase and is essential for parasite proliferation." (PMID 31492965, 2020). "First, host cells were transfected with an UHRF1 promoter-luciferase (UHRF1-luc) reporter plasmid, followed by infection with the virulent RH strain of T. gondii." (PMID 31492965, 2020). "We demonstrate that activated UHRF1 is recruited to the CCNB1 promoter during infection and induces epigenetic modifications, resulting in the formation of a heterochromatin environment and repression of the CCNB1 promoter activity." (PMID 31492965, 2020). "Infection of CRC cells with sh-UHRF1 promoted the expression of the KISS1 protein and inhibited the expression of PI3K/NF-κB signaling pathway-related proteins." (PMID 31803739, 2019). "A group of Treg-signature genes (Areg, Arhpag20, Bub1b, Ccl12, Ccr5, Il1r1, Mki67 (Ki67) Ncf1, Nrp2, Tnfrsf9, Tcf19, Uhrf1, and Wnt3) were expressed at higher levels in IFNARfl/fl x Foxp3YFP-Cre mice than WT controls on day 5 Armstrong infection." (PMID 29672594, 2018). "Interestingly, in our study, UHRF1 deletion decreased active infection but increased latency reversal." (PMID 38411080, 2024). "To investigate the role of UHRF1 in the regulation of HIV-1 replication, we first analyzed whether the depletion of UHRF1 would affect cell infection with the replication-competent HIV-1NL4-3 virus." (PMID 34465029, 2021). "The results also show a significant increase in UHRF1 mRNA expression at 3 h post-infection." (PMID 31492965, 2020). "Preliminary work on PRU (type II) parasites, which contain the avirulent ROP16 isotype showed a graduate, but much less pronounced upregulation of UHRF1, while the cell cycle shows a considerably delayed (12–24 h) and less pronounced block, compared to type I infection (our own observation)." (PMID 31492965, 2020). "Infection significantly induced UHRF1 promoter activity at 3 h post-infection." (PMID 31492965, 2020). "We observed a reversal of the infection-induced cyclin B1 kinetics in UHRF1 knock-down cells." (PMID 31492965, 2020). "This suggests two independent roles for UHRF1 at different stages of HIV infection, where UHRF1 is required for the establishment of initial infection but then hinders HIV-1 production and contributes to the maintenance of latency." (PMID 38411080, 2024).
infection (continued). "UHRF1 was robustly recruited to HIV-1 5′-LTR, and HIV-1NL4-3 infection significantly abolished the recruitment of UHRF1 to HIV-1 LTR." (PMID 34465029, 2021). "To establish if UHRF1 is directly involved in cyclin B1 downregulation, we examined the recruitment of UHRF1 to the CCNB1 promoter during infection, by chromatin immunoprecipitation (ChIP) assay." (PMID 31492965, 2020). "Six days following infection, the cells were electroporated with crRNPs in technical triplicate using either a non-targeting control guide (NTC-03) or the TRAF2/UHRF1 guide resulting in the strongest phenotype in our previous screen (TRAF2-01 and UHRF1-01)." (PMID 38411080, 2024). "Six hours post-infection, UHRF1 protein expression was increased in the presence or not of cytochalasin D. These results confirmed that the increase in UHRF1 expression is due to rhoptry secreted proteins and does not need parasite penetration." (PMID 31492965, 2020).
blood cancer (3 papers, 2021 to 2023). "The integrated epigenetic UHRF1 is overexpressed in many solid and hematological tumors and its overexpression is considered as a main cause of enhanced cell proliferation and defective apoptosis through the inhabitation of several tumor suppressor genes." (PMID 35566130, 2022). "Consistently, UHRF1 showed higher expression level in AML patients and higher stage of blood cancer." (PMID 37573395, 2023).
adenocarcinoma (2 papers, 2010 to 2017). A common cancer characterized by the presence of malignant glandular cells. "UHRF1 overexpression was also confirmed in another study including 105 NSCLC tissues (55 adenocarcinomas and 50 squamous cell carcinomas) along with DNMT1, DNMT3A and DNMT3B." (PMID 28881702, 2017).
metabolic disease (2 papers, 2019 to 2024). A congenital disorder (due to inherited enzyme abnormality) or acquired (due to failure of a metabolically important organ) disorder resulting from an abnormal metabolic process. "The potential role of UHRF1 in cytokine secretion through epigenetic alterations leading to inflammation and metabolic disorders has also been reported." (PMID 38789534, 2024). "In conclusion, we uncovered key DEGs and molecular pathways altered in UHRF1-null cells using transcriptomics analysis, which offered insights into candidate adipogenesis regulators with therapeutic potential for metabolic diseases." (PMID 38789534, 2024).
UHRF1 also shares sentences with these, for which no sentence is quoted: cervical squamous cell carcinoma (5 papers); inflammatory bowel disease (3); metastatic tumors (3); Hepatic fibrosis (2); nasopharyngeal carcinoma (2); prostate adenocarcinoma (2); psoriasis (2); rheumatoid arthritis (2); abdominal aortic aneurysm (1); adenoma (1); allergic asthma (1); amnesia (1); B cell acute lymphocytic leukemia (1); benign neoplasm of kidney (1); breast invasive carcinomas (1); breast tumor (1); childhood asthma (1); chronic myeloid leukemia (1); chronic pancreatitis (1); diabetes (1); diabetic nephropathy (1); focal segmental glomerulosclerosis (1); gynecological tumors (1); hematological malignancies (1); Hepatic steatosis (1); Immunodeficiency (1); laminopathy (1); large cell lung carcinoma (1); mesenchymal tumors (1); microphthalmia (1).
A further 19 diseases each share a sentence with UHRF1 in 1 paper.